PTN (pleiotrophin)
Diseases named in the same sentence as PTN in open-access papers (continued):
Sharing a sentence is not in itself a finding about the gene and the disease.
Cerebral ischemia (1 paper, 2025). Restriction of arterial blood supply to the brain associated with insufficient oxygenation to support the metabolic requirements of the tissue. "In cerebral ischemia‐reperfusion injury, the pleiotrophin (PTN)/syndecan‐3 pathway mediates the neuroprotective effect in heparin therapy." (PMID 40692664, 2025).
chronic hepatitis (1 paper, 2023). An active inflammatory process affecting the liver for more than six months. "PTN have been implicated in numerous inflammatory conditions such as chronic hepatitis." (PMID 37259127, 2023).
colon adenocarcinoma (1 paper, 2025). "We first determined the relationship between the PTN expression and clinicopathological characteristics with the samples of colon adenocarcinoma (COAD) bulk transcriptome dataset from The Cancer Genome Atlas (TCGA) cohort." (PMID 40069574, 2025).
colorectal adenocarcinoma (1 paper, 2025). The most common type of colorectal carcinoma. "The TIMER 2.0 database shows a positive correlation between PTN, THBS2, and COL1A2 expression and immune cell infiltration in CAFs of colorectal adenocarcinoma (COAD) and rectal adenocarcinoma (READ)." (PMID 40242441, 2025).
dementia (1 paper, 2024). Loss of intellectual abilities interfering with an individual's social and occupational functions. "We found the growth differentiating factor-15 (GDF-15) and pleiotrophin (PTN) proteins to be associated with the AD-PS dementia risk scores in cognitively normal individuals." (PMID 38438772, 2024).
demyelinating disease (1 paper, 2025). A broad group of disorders that affect the myelin sheaths that cover the neurons. "Thus, PTN has great potential to improve remyelination and neuroprotective strategies in the treatment of demyelinating diseases or any injury." (PMID 40083634, 2025).
demyelination (1 paper, 2022). "More important, ectopic expression of PTN by a retrovirus accelerated the rate of remyelination in a mouse model of LPC-induced demyelination." (PMID 35143418, 2022).
ductal carcinomas (1 paper, 2007). "In particular, transcription regulators (ATF3, PIGR), genes encoding proteins with cytokine and growth factor activity (PTN, CX3CL1) and genes encoding proteins involved in ion transport and metabolism (ATP1A2, MMP7) were downregulated in ductal carcinomas when compared with normal cells." (PMID 17389037, 2007).
endometriosis (1 paper, 2019). The growth of functional endometrial tissue in anatomic sites outside the uterine body. "PTN is a member of a highly conserved human gene family and is a key gene in the process of endometriosis and regulates multiple functions, including apoptosis, cell cycle, cell proliferation, cell differentiation, progesterone and estrogen production, and angiogenesis." (PMID 31879572, 2019).
esophageal carcinoma (1 paper, 2022). A primary or metastatic malignant neoplasm involving the esophagus. "PTEN downregulation is also documented in periodontitis and P. ginivalis, and the keystone periodontal pathogen was found to promote esophageal carcinoma cell by modulation of PTN signaling." (PMID 35132337, 2022).
ganglioglioma (1 paper, 2023). A well differentiated, slow growing neuroepithelial neoplasm composed of neoplastic, mature ganglion cells and neoplastic glial cells. "FGF/FGFR and/or PDGF/PDGFR antagonism may also be important in the context of ganglioglioma, either in combination with PTN-PTPRZ1 antagonism or on their own." (PMID 36966348, 2023).
Hepatitis (1 paper, 2017). Inflammation of the liver. "The median serum PTN level in the 25 patients with HBV‐related hepatitis was 981.29 pg/ml (mean = 981.29 ± 261.82 pg/ml)." (PMID 28557334, 2017).
hyperglycaemia (1 paper, 2017). "This phenomenon leads to abnormal blood glucose metabolism in liver tissue, suggesting that hyperglycaemia may promote the lipogenesis of hepatocytes through the AP‐1/PTN/N‐syndecan/PI3K/Akt/mTORC1 pathway." (PMID 28557334, 2017).
Infertility (1 paper, 2014). "This is in contrast to the infertility phenotype previously reported in female PTN/MK double knockout mice." (PMID 25380037, 2014).
inflammatory bowel disease (1 paper, 2018). A spectrum of small and large bowel inflammatory diseases of unknown etiology. "In some other reports, PTN was found not the only activation of PTPRZ1 pathway, inflammation and immune can also activate the PTPRZ1 pathway, such as interleukin (IL)-34, an important receptor of PTPRZ1, promotes the expression of PTPRZ1 in inflammatory bowel disease (IBD)." (PMID 30497491, 2018).
liver fibrosis (1 paper, 2023). "In conclusion, this study found that PTN derived from CAFs participated in hepatocarcinogenesis by regulating fibrosis, and that PTN may mediated the effects of CAF on HBV infection associated with liver fibrosis in HCC." (PMID 37259127, 2023).
lymph node metastasis (1 paper, 2018). "Moreover, some studies have demonstrated that the PTN expression is associated with certain clinical characteristics, such as lymph node metastasis (LNM), distant metastasis (DM), clinical stages and overall survival (OS), while the results of some other researches are conflicting with them." (PMID 30427932, 2018).
lymphoblastic leukemia (1 paper, 2009). "Pleiotrophin (PTN) is up-regulated in human endometrial epithelial cells, and annexin A1 (ANXA1) is up-regulated in a lymphoblastic leukemia cell line." (PMID 19594897, 2009).
macrodactyly (1 paper, 2012). "Pleiotrophin is a promising candidate gene for the pathogenesis of macrodactyly because it promotes growth of nearly all the tissues affected by macrodactyly, including nerve, skin, bone, and cartilage." (PMID 22848377, 2012). "One mechanism whereby PTN overexpression might result in macrodactyly was recently suggested by the discovery of an activating AKT1 mutation in Proteus syndrome." (PMID 22848377, 2012).
malignant glioma (1 paper, 2024). A grade III or grade IV glioma arising from the central nervous system. "The interaction between malignant glioma cells and CAFs was mainly conducted through PTN-NCL and PPIA-BSG signaling pathways." (PMID 39033204, 2024).
medullary thyroid cancer (1 paper, 2016). "PTN/Tg was also elevated in the one nodule containing medullary thyroid cancer (2.9 ng/mg)." (PMID 26914549, 2016). "PTN was previously reported to be overexpressed in medullary thyroid cancer, but the expression of PTN in PTCs has not been investigated." (PMID 26914549, 2016).
metastatic colorectal cancer (1 paper, 2025). "Targeting PTN might be a promising strategy for the treatment of metastatic colorectal cancer." (PMID 40069574, 2025).
Mitral regurgitation (1 paper, 2024). An abnormality of the mitral valve characterized by insufficiency or incompetence of the mitral valve resulting in retrograde leaking of blood through the mitral valve upon ventricular contraction. "In fibrosis caused by mitral regurgitation, PTN is upregulated in the myocardial transcriptome, suggesting its role in cardiac remodeling." (PMID 39722892, 2024).
neovascular glaucoma (1 paper, 2015). "While the sample size is small, at present, our unpublished data on the effect of anti-VEGF therapy on PTN expression in neovascular glaucoma patients complicated by proliferative diabetic retinopathy also have the same results." (PMID 25617851, 2015).
neural tumors (1 paper, 2016). "PTN expression was significantly higher in the classical subtype as compared to mesenchymal, pro-neural and neural tumors." (PMID 27806344, 2016).
neuritis (1 paper, 2011). A neuropathy arising from inflammation of one or more nerves. "Pleiotrophin is also known as neurite growth-promoting factor 1 (NEGF1), has mitotic activity and influences the growth of neuritis." (PMID 21408165, 2011).
neuroendocrine tumour (1 paper, 2002). "Since PTN is expressed by endocrine cells, we were interested to investigate whether its expression is a feature of the neuroendocrine tumour SCLC and whether it can be detected within the serum of patients with this tumour." (PMID 11953815, 2002).
preeclampsia (1 paper, 2025). Preeclampsia is a hypertensive disorder of pregnancy that is characterized by new-onset hypertension with proteinuria presenting after 20 weeks of gestation, and depending on mild or severe forms may initially present with severe headache, visual disturbances, and hyperreflexia. "Our research showed that SPP1, Annexin, MIF, Visfatin, VEGF, Galectin, PTN, and CCL signalings were significantly inhibited among the three subtypes of macrophages in the preeclampsia group." (PMID 40216654, 2025).
protein misfolding diseases (1 paper, 2016). "The proteins encoded by APLP2, PTN, DCN, GPNMB, P4HB, and PDIA3, have been associated with either protein misfolding diseases or TSEs but their specific role in prion protein degradation has not been described." (PMID 26807844, 2016).
retinal degeneration (1 paper, 2025). Degeneration of the retina. "Relative to VEGF, the heparin-binding growth factors MDK/PTN are poorly studied in retinal degenerations." (PMID 40251274, 2025).
secondary progressive multiple sclerosis (1 paper, 2024). A multiple sclerosis with a clinical course characterized by a progressive accumulation of neurological disability, independent of relapses, following an initial relapsing-remitting (RR) phase. "PTN and ADGRG1 were also significantly different between relapsing–remitting multiple sclerosis and secondary progressive multiple sclerosis (FDR = 0.0053 and FDR = 0.041, respectively)." (PMID 38978729, 2024).
serous adenocarcinoma (1 paper, 2012). An adenocarcinoma that is characterized by the presence of papillary patterns and cellular budding. "Furthermore, two independent gene expression studies show that NDC80, NUF2 and PTN were significantly aberrantly overexpressed in serous adenocarcinomas." (PMID 23056589, 2012).
serous ovarian cancer (1 paper, 2025). "Present study underscores the critical role of PTN signaling in shaping the tumor microenvironment (TME) of high-grade serous ovarian cancer (HGSOC)." (PMID 40416874, 2025).
serous ovarian tumor (1 paper, 2025). "PTN levels in serous ovarian tumor tissues were on average 3.5-fold higher relative to normal tissue and PTN is detectable in serum samples of patients with EOC." (PMID 40416874, 2025).
thyroid nodule (1 paper, 2016). A small circumscribed mass in the THYROID GLAND that can be of neoplastic growth or non-neoplastic abnormality. "The findings raise the possibility that measurement of the PTN to Tg ratio may provide useful diagnostic and/or prognostic information in the evaluation of thyroid nodules." (PMID 26914549, 2016).
viral infection (1 paper, 2011). "Thus, over-expression of PTN mainly occurred in astrocytes, not as a non-specific consequence of viral infection, but only in animals treated with the vector carrying the PTN genetic code." (PMID 21649894, 2011).
tumor (157 papers, 2002 to 2026). "The multi-color immunofluorescence staining revealed that tumor cells exhibiting higher PTN expression were closely associated with fibroblasts infiltration in stromal regions, showing a positive correlation with tumor metastasis." (PMID 40069574, 2025). "In line with the high PTPRZ1 expression in embryonic stem cells, PTPRZ1 is preferentially expressed in GBM stem cells and mediates the stimulatory effects of PTN secreted by tumor-associated macrophages on GBM growth." (PMID 37175798, 2023). "PTN re-expression in adults is associated with tumor development, metastasis and angiogenesis with elevated expression reported in several cancer sites." (PMID 35365620, 2022). "Our results showed that PTN is an important regulator of lipogenesis and can regulate genes encoding proteins associated with de novo lipogenesis in tumour cells." (PMID 28557334, 2017). "Heparin affin regulatory peptide (HARP), also called pleiotrophin, is a heparin-binding, secreted factor that is overexpressed in several tumours and associated to tumour growth, angiogenesis and metastasis." (PMID 21624116, 2011). "PTN is an angiogenic factor that stimulates tumour-associated vascular formation in many malignancies." (PMID 19826427, 2009). "A recent study investigated PTN in the serum of patients with various cancers and the results indicated that PTN is associated with the presence of tumour." (PMID 11953815, 2002). "We wondered whether the CD44+ tumor cells with high stemness gained the enhanced invasive and metastasis potential through a PTN-dependent and CAFs-associated manner." (PMID 40069574, 2025). "Since Hep3B was HBV-positive cell whereas Huh7 was HBV-negative cell, we hypothesized that HBV infection may play an important role in initiating PTN-mediated tumor-associated fibrosis in HCC." (PMID 37259127, 2023). "Consequently, inhibition of PTN, pharmacologically or genetically, reduces the accumulation of tumor-associated neutrophils and reverts local immune suppression, resulting in increased T cell activation and attenuated metastasis." (PMID 36828390, 2023). "Indeed, several upregulated genes in the H2BE76K mutant cells, such as WNT7B and PTN, are involved in promoting metastasis-associated tumor cell phenotypes, including increased clonogenicity." (PMID 33548228, 2021). "Moreover, the gene encoding pleiotrophin (Ptn) is a proto-oncogene, and subsequently the levels of this protein are increased in tumour and neoplastic processes." (PMID 34502170, 2021). "It has been demonstrated that PTPRZ1 binding to PTN could activate calmodulin to induce nitric oxide formation, which causes tumour blood vessel formation and tumour cell proliferation in vitro." (PMID 30497491, 2018). "Additionally, upregulated pleiotrophin expression has been associated with biological events that involve cellular proliferation and differentiation such as tissue regeneration, bone repair, inflammatory processes, hypoxia, tumor growth and angiogenesis." (PMID 37484951, 2023). "However, further experiments might be necessary to identify the molecular mechanisms underlying the dysregulation of PTN in lipid metabolism in tumour cells and normal cells." (PMID 28557334, 2017). "We examine the expression and function of PTN at a cellular level and explore the interplay between PTN and the tumour microenvironment." (PMID 42193935, 2026). "TPST1-high tumor cells exhibited proliferative enrichment and potential interaction with myeloid cells via PTN-NCL and EREG/AREG-EGFR signaling pathways." (PMID 41838327, 2026). "Our analysis identified the pleiotrophin (PTN) signaling pathway as a significant network modulating the tumor cells of HGSOC." (PMID 40416874, 2025). "TC tumor cells expressed receptors for multiple signaling pathways, including MK, PTN, SPP1, TWEAK, EGF, and IFN-II (IFNG) (blue frames)." (PMID 41228323, 2025).
tumor (continued). "MK pathway activation was observed across all cancers, involving both tumor cells and CAFs, while PTN and ANGPTL pathways, which share receptors with MK, were expressed dominantly in pericytes." (PMID 41228323, 2025). "The study proposed and validated a NEFH+ tumor cell–PTN–NCL–CAFs conversion axis in PCa, underscoring the central role of the C1 ABCA8+ subtype in tumor progression." (PMID 41514658, 2025). "In this way, the PTN-TNF molecular axis-mediated cellular interactions create a vicious cycle in the HER2 + IBC tumour microenvironment centred on the inflammatory response, which prevents the formation of a more immunosuppressive microenvironment." (PMID 40624675, 2025). "PTN is a multifunctional growth factor known for its angiogenic properties and role in tumor growth and metastasis." (PMID 40722679, 2025). "CD44+ tumor cells then triggered the phenotypic transition of CAFs into iCAF-like and myCAF-like cells through PTN signaling." (PMID 40069574, 2025). "We identified tumor-derived PTN as a promoter to drive lymph node metastases in a CAF-dependent manner, potentially offering a promising target for overcoming CRC relapse." (PMID 40069574, 2025). "We found a strong correlation between high expression of PTN molecules in HER2 + IBC tumour cells and their highly invasive characteristics and highly immunosuppressive TME." (PMID 40624675, 2025). "Consistent with this, our experimental results indicate that HER2 + IBC tumour cells can mediate endothelial necroptosis through the PTN-NCL-TNF signaling axis to promote the expression of IL-6 and IL-8." (PMID 40624675, 2025). "The results of cell communication analysis suggest that tumour cells can establish an interaction relationship with CAF by expressing PTN." (PMID 40624675, 2025). "On the basis of the differences in cellular interactions, we concluded that PTN-mediated interactions play an important role in the formation of an immunosuppressive microenvironment in IBC tumours." (PMID 40624675, 2025). "IHC staining results confirmed that the level of tumor cell-expressed PTN was much higher in leading edge than that in central area of tumor regions." (PMID 40069574, 2025). "Mechanistically, CD44+ tumor cells at the edge can secrete PTN, a PDGF-inducible cytokine, which acts as a chemokine, aggregates CAFs, and leads to their transformation to iCAF-like or myCAF-like cells." (PMID 40069574, 2025). "The fluorescence staining results for CD44, PTN and Collagen revealed that CD44high-PTNhigh tumor cells was observed not only specifically at the leading edge, but also near fibroblasts infiltrated within tumor microenvironment." (PMID 40069574, 2025). "At spatial and single-cell resolution, REN-expressing tumor cells promoted NK cell exhaustion via PTN-NCL and COL4A1-CD44 ligand-receptor interactions, while showing limited impact on T cell dysfunction." (PMID 40534868, 2025). "Co-implantation of M2-like macrophages (MLCs) enhanced GSC-driven tumor growth, but silencing PTN expression in MLCs attenuated their pro-tumorigenic activity." (PMID 38732975, 2024). "Cells in the high-scoring group activated most of the signaling pathways associated with tumor initiation and progression, including TGF-β, CCL, PTN, FGF, VEGF, and EGFR." (PMID 39456925, 2024). "The interaction between NCL and PTN plays a vital role in tumor progression, especially in tumor angiogenesis, tumor growth, and chemotherapy resistance." (PMID 38806553, 2024). "This analysis suggests an important role of MDK and PTN signaling in tumor proliferation in Group 3 and Group 4 MBs, presenting a potential drug target." (PMID 39659836, 2024). "Elevated levels of Pleiotrophin (PTN) in HNC contribute to aggressive tumor behavior and correlate with poor prognosis." (PMID 39628997, 2024). "Pleiotrophin (PTN) is a heparin-binding growth factor of the family of midkine, a tumor promoting factor." (PMID 36614248, 2023).